PAAF1 (proteasomal ATPase associated factor 1)
Description:
Inhibits proteasome 26S assembly and proteolytic activity by impairing the association of the 19S regulatory complex with the 20S core. In case of HIV-1 infection, recruited by viral Tat to the HIV-1 promoter, where it promotes the recruitment of 19S regulatory complex through dissociation of the proteasome 26S. This presumably promotes provirus transcription efficiency. Protects SUPT6H from proteasomal degradation.
Synonyms: WDR71; FLJ11848; Rpn14; PAAF
Tractability: PROTAC: ubiquitination databases record sites on it; its protein half-life has been measured.
Gene: Protein-coding gene on chromosome 11 (73,876,699 to 73,931,114, forward strand). Ensembl gene ENSG00000175575.
Subcellular location (Human Protein Atlas): Nucleoplasm; Cytosol
Pathways (Reactome):
Metabolism of proteins: Proteasome assembly
Gene Ontology:
Molecular function: protein binding
Cellular component: proteasome complex; cytosol
Genetic constraint (gnomAD): Loss-of-function variants: 31 observed, 36.54 expected, observed/expected ratio (o/e) 0.85, 90% interval 0.64 to 1.14. The upper end of that interval is the gene's LOEUF score, 1.14, which puts it in group 5 of 6, group 1 being the genes least tolerant of losing a copy. Missense variants: 340 observed, 391.54 expected, observed/expected ratio (o/e) 0.87, 90% interval 0.79 to 0.95. Synonymous variants: 149 observed, 146.6 expected, observed/expected ratio (o/e) 1.02, 90% interval 0.89 to 1.16.
Homologues: Orthologues: macaque PAAF1 (98% identical), dog PAAF1 (95% identical), guinea pig PAAF1 (95% identical), pig PAAF1 (95% identical), rabbit PAAF1 (95% identical), chimpanzee PAAF1 (85% identical), tropical clawed frog thul16 (67% identical), tropical clawed frog paaf1 (51% identical), Caenorhabditis elegans Y39G10AR.9 (27% identical). Paralogues in human: FBXW7 (17% identical), BTRC (15% identical), FBXW11 (14% identical), TRAF7 (13% identical), WDR49 (13% identical), WDR86 (12% identical), EFCAB8 (11% identical), WDR64 (11% identical), FBXW9 (11% identical), FBXW12 (9% identical), FBXW8 (8% identical), WDR54 (7% identical), and 2 more.
Diseases named in the same sentence as PAAF1 in open-access papers:
PAAF1 is named in the same sentence as 5 diseases in open-access papers, as found by Europe PMC text mining. Sharing a sentence is not in itself a finding about the gene and the disease. The quoted sentences say what the papers report.
Parkinson disease (1 paper, 2024). A progressive degenerative disorder of the central nervous system characterized by loss of dopamine producing neurons in the substantia nigra and the presence of Lewy bodies in the substantia nigra and locus coeruleus. "Rpn14/PAAF1 is a newly identified key factor functioning as link between α‐syn and cytotoxicity based on disturbances in cellular proteostasis as it is found in Parkinson's disease." (PMID 38415292, 2024).
cancer (3 papers, 2011 to 2022). A tumor composed of atypical neoplastic, often pleomorphic cells that invade other tissues. "Gene ontology analysis revealed that many of the differentially expressed genes following either PAAF1 or Spt6 knockdown are implicated in cancer." (PMID 22316138, 2012). "Transcriptional profiling followed by ChIP identified a subset of cellular genes that are regulated in a similar fashion to HIV-1 by Spt6 and/or PAAF1, including many that are involved in cancer, such as BRCA1 and BARD1." (PMID 22316138, 2012). "Since such genes are frequently deregulated in cancer, Ingenuity Pathway analysis showed that knockdown of PAAF1 or, more particularly, Spt6, impacted strongly on genes involved in cancer." (PMID 22316138, 2012). "Transcriptional profiling in either PAAF1 or Spt6 knockdown cells followed by ChIP analysis at selected genes revealed an important role for Spt6 and PAAF1 in controlling the expression of a subset of genes involved in cancer." (PMID 22316138, 2012). "Three genes, PPP1CA, PAAF1, and TGOLN2 were significantly upregulated in cancer tissues (P=0.0154, P=0.0298, and P=0.0312 respectively)." (PMID 21847129, 2011).
tumor (1 paper, 2012). "In contrast, a subset of genes including tumor suppressors, such as BRCA1, BARD1 and BLM, were highly deregulated by loss of Spt6 but were only modestly affected or unaffected by loss of PAAF1, even though Spt6 level in these cells was significantly diminished." (PMID 22316138, 2012).
PAAF1 also shares sentences with these, for which no sentence is quoted: breast carcinoma (1 paper); infection (1).